ICMT (isoprenylcysteine carboxyl methyltransferase)
Description:
Catalyzes the post-translational methylation of isoprenylated C-terminal cysteine residues.
Synonyms: PPMT; pcCMT; HSTE14; MST098; MSTP098; PCMT
Tractability: Small molecule: a high-quality ligand is known; it belongs to a druggable protein family. Antibody: UniProt predicts a signal peptide or a membrane-spanning region. PROTAC: ubiquitination databases record sites on it; its protein half-life has been measured; a small molecule that binds it is known.
Target class: Enzyme; Transferase
Gene: Protein-coding gene on chromosome 1 (6,221,193 to 6,235,972, reverse strand). Ensembl gene ENSG00000116237.
Subcellular location: Endoplasmic reticulum membrane
Pathways (Reactome):
Metabolism of proteins: Gamma carboxylation, hypusinylation, hydroxylation, and arylsulfatase activation
Signal Transduction: RAS processing
Gene Ontology:
Molecular function: protein binding; protein C-terminal S-isoprenylcysteine carboxyl O-methyltransferase activity
Biological process: protein targeting to membrane; cellular response to alkaline pH
Cellular component: endoplasmic reticulum; endoplasmic reticulum membrane; membrane
Genetic constraint (gnomAD): Loss-of-function variants: 10 observed, 28.07 expected, observed/expected ratio (o/e) 0.36, 90% interval 0.22 to 0.6. The synonymous counts are far from expectation, so gnomAD's model fits this gene poorly and the ratio says little. Missense variants: 261 observed, 324.41 expected, observed/expected ratio (o/e) 0.8, 90% interval 0.73 to 0.89. Synonymous variants: 183 observed, 144.84 expected, observed/expected ratio (o/e) 1.26, 90% interval 1.12 to 1.43.
Homologues: Orthologues: chimpanzee ICMT (99% identical), macaque ICMT (99% identical), guinea pig ICMT (97% identical), mouse Icmt (96% identical), rabbit ICMT (96% identical), rat Icmt (95% identical), tropical clawed frog icmt (70% identical), pig ICMT (65% identical), zebrafish icmt (62% identical), Drosophila melanogaster Icmt (48% identical), Caenorhabditis elegans M01E11.1 (32% identical), Caenorhabditis elegans icmt-1 (31% identical).
Diseases named in the same sentence as ICMT in open-access papers:
ICMT is named in the same sentence as 16 diseases in open-access papers, as found by Europe PMC text mining. Sharing a sentence is not in itself a finding about the gene and the disease. The quoted sentences say what the papers report.
progeria (4 papers, 2014 to 2023). "Inhibiting isoprenylcysteine carboxylmethyltransferase (ICMT)-associated activation of AKT-mTOR signaling has been found to improve progeria symptoms." (PMID 36833255, 2023). "Together, these results support the potential of the ICMT inhibitors, by themselves or in combination therapies, for treating progeria." (PMID 34281245, 2021). "In this context, the finding that genetic disruption of ICMT improved the phenotype in the ZMPSTE24 mouse model of progeria supported that a small molecule ICMT inhibitor could represent a new therapeutic strategy to address HGPS." (PMID 34281245, 2021). "More recent studies have indicated that targeting ICMT might be useful in treating the rare genetic disease progeria." (PMID 25552352, 2014). "Several studies have shown that cells or mouse models of progeria after treatment with either farnesyltransferase inhibitor (FTI), statins, or isoprenylcysteine carboxyl methyltransferase (ICMT) inhibitor could reverse some of the phenotypic changes occurring in these cells or tissues." (PMID 25510262, 2015).
breast carcinoma (3 papers, 2020 to 2024). "Further validating the role of ICMT in the regulation of the expression of these genes, we subjected multiple breast cancer cell lines to ICMT inhibitor treatment." (PMID 34610973, 2021). "Moreover, our data suggest that inhibition of ICMT by knockout and knockdown markedly attenuates Ras-mediated inflammatory responses not only in vitro in macrophages and breast cancer cells, but also in vivo disease models." (PMID 32422978, 2020).
hepatocellular carcinoma (1 paper, 2020). A malignant tumor that arises from hepatocytes. "In support to this idea, high ICMT levels were found in hepatocellular carcinoma patients and ICMT overexpression enhanced proliferation and migration in normal liver cells." (PMID 33224889, 2020).
non-small cell lung carcinoma (1 paper, 2020). A group of at least three distinct histological types of lung cancer, including non-small cell squamous cell carcinoma, adenocarcinoma, and large cell carcinoma. "Similarly, ICMT overexpression in H1299 non-small cell lung carcinoma (NSCLC) cells increased clonogenic potential in vitro and tumorigenesis in a xenograft model." (PMID 33224889, 2020).
ovarian carcinoma (1 paper, 2021). A malignant neoplasm originating from the surface ovarian epithelium. "HMOX2, ICMT, MICU1, and TSPAN9 also positively correlated with CD73_1 and CD73_2 densities and short survival and have been shown to be involved in conferring chemoresistance in ovarian cancer." (PMID 33917869, 2021).
pancreatic cancer (1 paper, 2022). "Moreover, the expression of some proteins that are associated with the progression of pancreatic cancer, such as SYNE2, ICMT, and FAM172A, is regulated by HCQ." (PMID 36014414, 2022). "In addition, suppression of ICMT, a protein catalyzing the post-translational methylation of isoprenylated C-terminal cysteine residues, has been shown to inhibit proliferation and induce apoptosis of pancreatic cancer cells." (PMID 36014414, 2022). "Furthermore, HCQ may prevent the progression of pancreatic cancer by regulating the expression of nesprin-2 (SYNE2), protein-S-isoprenylcysteine O-methyltransferase (ICMT), and cotranscriptional regulator FAM172A (FAM172A)." (PMID 36014414, 2022).
cancer (14 papers, 2011 to 2024). A tumor composed of atypical neoplastic, often pleomorphic cells that invade other tissues. "In specific types of cancer cells, the increase in p21 is linked to the actions of the enzyme I isoprenylcysteine carboxylmethyltransferase (ICMT)." (PMID 39684919, 2024). "The inhibition of isoprenylcysteine carboxylmethyltransferase (ICMT) can be an effective pathway for RAS-associated cancer treatment." (PMID 35409064, 2022). "Indeed, ICMT inhibitors have been proposed for treating Ras-associated tumorigenic responses in various cancers." (PMID 32422978, 2020). "ICMT itself is also a promising therapeutic target for many cancers since it is critical for malignant transformation in Ras-driven cancers." (PMID 35628237, 2022). "Previous studies of ICMT and Ras have been limited to cancer research; this study is the first to examine its role in the context of inflammatory stimuli at molecular levels." (PMID 32422978, 2020). "Several reports have shown that glabrol inhibits the cancer targets cytochrome P450 1B1 enzyme and isoprenylcysteine carboxyl methyltransferase." (PMID 31749783, 2019). "ICMT activity is essential for cell growth and development in higher eukaryotes, and inhibition of GTPase methylation has become an attractive target in cancer therapy to inactivate prenylated oncoproteins." (PMID 28729673, 2017). "The inhibition of ICMT is an emerging and innovative area in the development of potential anti-cancer therapeutics." (PMID 28631011, 2017). "Cancer Therapeutics CRC PTY Ltd has developed ICMT inhibitors using a formula based on pyrazin-2-amine." (PMID 28631011, 2017). "ICMT is a potential target for cancer therapeutics as this enzyme catalyses the final step in post translational modification, where carboxyl methylation of oncogenic proteins takes place." (PMID 29023425, 2017). "Numerous reports have also demonstrated that inhibition of ICMT leads to an anti-proliferative effect in cancer." (PMID 28631011, 2017). "In 2011, Patrick J. Casey, Rudi A. Baron, and Ann M. Winter-Vann at Duke University applied for a patent for ICMT inhibitors with potential anti-cancer activity." (PMID 28631011, 2017). "Numerous studies have shown the potential of targeting ICMT and its substrates in cancers." (PMID 32561852, 2020). "Among them, Rac1 and ICMT were selected for further experimental validation, because Rac1 is frequently activated in tumor tissues and promotes cancer metastasis, while ICMT plays an essential role in activating Rho GTPase, including Rac1, and inhibition of ICMT leads to decrease of GTP-bound Rac1." (PMID 25361001, 2014). "ICMT inhibitors have been shown to regulate the activation of RAS, making them a potential therapeutic approach against cancer." (PMID 34947990, 2021). "In this study, we provide compelling evidence that supports a previously unidentified role of ICMT in the regulation of TAZ degradation via modulating the function of mutant KRAS and its downstream RAF–MEK signaling to support cancer cell self-renewal." (PMID 32561852, 2020). "Taken together, these findings support a role for ICMT in regulating TAZ protein levels, and that this property is important in the self-renewal ability of cancer cells." (PMID 32561852, 2020). "The enzyme involved in methylation of the prenylated protein, isoprenylcysteine carboxyl methyltransferase (ICMT), is now being studied for cancer metastasis and results appear to be promising." (PMID 25552352, 2014).
tumor (4 papers, 2014 to 2023). "These discrepant results illustrate that the role of ICMT in neoplasia is context dependent and likely explained by the fact that ICMT methylesterifies hundreds of CaaX protein substrates." (PMID 33579760, 2021). "Moreover, the level of miR-100 was negatively related to the expression of ICMT and Rac1 in tumor tissues." (PMID 25361001, 2014).
ICMT also shares sentences with these, for which no sentence is quoted: atopic dermatitis (1 paper); bladder cancer (1); cervical carcinoma (1); gastritis (1); genetic disease (1); Hashimoto thyroiditis (1); hyperhomocysteinemia (1); oral squamous cell carcinoma (1).